RN7SL683P (RNA, 7SL, cytoplasmic 683, pseudogene)
Gene: Miscellaneous RNA gene on chromosome 14 (71,448,689 to 71,448,958, forward strand). Ensembl gene ENSG00000242330.
Homologues: Orthologues: chimpanzee Metazoa_SRP (97% identical), macaque Metazoa_SRP (87% identical). Paralogues in human: RN7SL1 (84% identical), RN7SL2 (83% identical), RN7SL296P (83% identical), RN7SL3 (82% identical), RN7SL113P (81% identical), RN7SL553P (80% identical), RN7SL43P (80% identical), RN7SL45P (80% identical), RN7SL575P (80% identical), RN7SL743P (80% identical), RN7SL220P (79% identical), RN7SL336P (79% identical), and 705 more.